SNORD28 (small nucleolar RNA, C/D box 28)
Synonyms: U28; SNORD28A; RNU28
Gene: Small nucleolar RNA gene on chromosome 11 (62,854,621 to 62,854,695, reverse strand). Ensembl gene ENSG00000274544.
Gene Ontology:
Biological process: RNA processing
Cellular component: nucleolus
Homologues: Orthologues: chimpanzee SNORD28 (100% identical), macaque SNORD28 (99% identical), dog SNORD28 (91% identical), pig SNORD28 (91% identical), rabbit SNORD28 (83% identical), rat Snord28b (81% identical), mouse Gm24453 (79% identical), guinea pig SNORD28 (77% identical), tropical clawed frog SNORD28 (63% identical). Paralogues in human: SNORD28B (84% identical), SNORA108 (68% identical).
Diseases named in the same sentence as SNORD28 in open-access papers:
SNORD28 is named in the same sentence as 7 diseases in open-access papers, as found by Europe PMC text mining. Sharing a sentence is not in itself a finding about the gene and the disease. The quoted sentences say what the papers report.
breast carcinoma (1 paper, 2015). "In addition, up-regulation of SNORD28 but not SNORD25 in breast cancer tissues also indicates existence of extensive posttranscriptional regulation." (PMID 26061048, 2015).
breast tumours (1 paper, 2015). "The regulatory role of sno-miR-28 is further confirmed by our expression profiling studies which relate SNHG1, SNORD28 and sno-miR-28 to breast tumours." (PMID 26061048, 2015). "In addition, SNHG1, SNORD28 and sno-miR-28 are all significantly upregulated in breast tumours and the overexpression of sno-miR-28 promotes breast epithelial cell proliferation." (PMID 26061048, 2015).
infection (1 paper, 2022). The state of being infected such as from the introduction of a foreign agent such as serum, vaccine, antigenic substance or organism. "The silencing of SNORA/Ds encoded within RPS11 (SNORD35B), SNHG3 (SNORA73A, SNORA73B), and SNHG1 (SNORD22, SNORD25, SNORD26, SNORD27, SNORD28, SNORD29, SNORD30, SNORD31) inhibited infection with influenza A virus." (PMID 36430145, 2022).
SNORD28 also shares sentences with these, for which no sentence is quoted: Ataxia (1 paper); cerebellar degeneration (1); tumor (1); viral infections (1).